TMTC3 (transmembrane O-mannosyltransferase targeting cadherins 3)
Description:
Transfers mannosyl residues to the hydroxyl group of serine or threonine residues. The 4 members of the TMTC family are O-mannosyl-transferases dedicated primarily to the cadherin superfamily, each member seems to have a distinct role in decorating the cadherin domains with O-linked mannose glycans at specific regions. Also acts as O-mannosyl-transferase on other proteins such as PDIA3. Involved in the positive regulation of proteasomal protein degradation in the endoplasmic reticulum (ER), and the control of ER stress response.
Synonyms: FLJ90492; SMILE; LIS8
Tractability: Antibody: UniProt predicts a signal peptide or a membrane-spanning region. PROTAC: ubiquitination databases record sites on it; its protein half-life has been measured.
Target class: Enzyme; Transferase
Gene: Protein-coding gene on chromosome 12 (88,142,181 to 88,199,887, forward strand). Ensembl gene ENSG00000139324.
Subcellular location: Membrane; Endoplasmic reticulum
Gene Ontology:
Molecular function: dolichyl-phosphate-mannose-protein mannosyltransferase activity; protein binding; mannosyltransferase activity
Biological process: positive regulation of proteasomal protein catabolic process; protein O-linked glycosylation via mannose; response to endoplasmic reticulum stress
Cellular component: endoplasmic reticulum; membrane
Genetic constraint (gnomAD): Loss-of-function variants: 40 observed, 72.23 expected, observed/expected ratio (o/e) 0.55, 90% interval 0.43 to 0.72. The upper end of that interval is the gene's LOEUF score, 0.72, which puts it in group 2 of 6, group 1 being the genes least tolerant of losing a copy. Missense variants: 810 observed, 987.25 expected, observed/expected ratio (o/e) 0.82, 90% interval 0.77 to 0.87. Synonymous variants: 318 observed, 348.99 expected, observed/expected ratio (o/e) 0.91, 90% interval 0.83 to 1.
Homologues: Orthologues: chimpanzee TMTC3 (99% identical), macaque TMTC3 (98% identical), dog TMTC3 (94% identical), rabbit TMTC3 (94% identical), pig TMTC3 (94% identical), guinea pig TMTC3 (92% identical), rat Tmtc3 (91% identical), mouse Tmtc3 (90% identical), tropical clawed frog tmtc3 (79% identical), zebrafish tmtc3 (74% identical), Drosophila melanogaster Tmtc3 (50% identical). Paralogues in human: TMTC2 (28% identical), TMTC4 (28% identical), TMTC1 (26% identical), CFAP70 (11% identical), TTC6 (11% identical), IFT88 (10% identical), TTC7B (10% identical), TTC7A (10% identical), TTC34 (9% identical), TTC16 (8% identical), BBS4 (8% identical), TTC13 (8% identical), and 2 more.
Diseases named in the same sentence as TMTC3 in open-access papers:
TMTC3 is named in the same sentence as 19 diseases in open-access papers, as found by Europe PMC text mining. Sharing a sentence is not in itself a finding about the gene and the disease. The quoted sentences say what the papers report.
cobblestone lissencephaly (4 papers, 2021 to 2023). "Meanwhile, the biallelic TMTC3 mutations result in cobblestone lissencephaly, intellectual disability, and epilepsy, in addition to the highlight on its possible implication in BC." (PMID 37069941, 2023). "Family studies show TMTC3 mutations being causative for cobblestone lissencephaly and periventricular nodular heterotopia with intellectual disability and epilepsy." (PMID 33436046, 2021). "This suggestions is supported by the known mutant phenotype in human TMTC3 (the mutation His67Asp introduces a charge swap and leads to cobblestone lissencephaly; H67 is the position in TMTC3 homologous to H89 in TMTC1)." (PMID 33436046, 2021). "TMTC3 (transmembrane and tetratricopeptide repeat containing 3) was involved in some neuronal cell migration diseases in humans, such as cobblestone lissencephaly." (PMID 36140679, 2022). "Mutations in the transmembrane protein TMTC3 (transmembrane and tetratricopeptide repeat containing 3), which does not contain obvious functional connections to α-dystroglycan, have been found in patients with cobblestone lissencephaly." (PMID 35069108, 2021).
breast carcinoma (3 papers, 2020 to 2023). "Furthermore, one patient harbored a duplication in TMTC3 gene which was found to be unregulated in breast cancer associated blood vessels and may therefore constitute a potentially anti-angiogenic target for breast cancer therapy." (PMID 33503040, 2021). "Considering the role of glycolysis inhibition as a novel therapeutic strategy for cancer, including breast cancer (BC), we wondered whether glycolysis could affect BC progression by regulating transmembrane O-mannosyltransferase-targeting cadherins 3 (TMTC3)." (PMID 37069941, 2023).
cognitive decline (1 paper, 2025). "Our investigations reveal that aging differentially modulates restraint stress-induced ER stress responses: while suppressing the upregulation of protective ER stress-related genes (Fmo2, Creb3l1, Tmtc3, Bak1), it promotes the induction of Pgap1 change associated with cognitive decline." (PMID 41200271, 2025).
esophageal adenocarcinoma (1 paper, 2022). A malignant tumor with glandular differentiation arising predominantly from Barrett mucosa in the lower third of the esophagus. "Moreover, in the UALCAN database, we found that the expression of TMTC3 in ESCC was higher than that in the other esophageal cancer subtype, esophageal adenocarcinoma (EAC)." (PMID 35982901, 2022).
esophageal squamous cell carcinoma (1 paper, 2023). Esophageal squamous cell carcinoma (ESCC) is a type of esophageal carcinoma (EC) that can affect any part of the esophagus, but is usually located in the upper or middle third. "We previously identified TMTC3 as an ER stress mediator under nutrient-deficiency condition in esophageal squamous cell carcinoma (ESCC), but the molecular mechanism in hypoxia is still unclear." (PMID 37752569, 2023).
hyperopia (1 paper, 2008). A refractive error in which rays of light entering the eye parallel to the optic axis are brought to a focus behind the retina, as a result of the eyeball being too short from front to back. "Five of them were upregulated during induction of hyperopia with positive lenses (DCX, NLGN1, QSER1, TMTC3, and LOC41695) and one was downregulated (GRHL3)." (PMID 18769560, 2008).
lissencephaly 8 (1 paper, 2020). Any lissencephaly (disease) in which the cause of the disease is a mutation in the TMTC3 gene. "As the human TMTC3 gene is associated with a neuronal migration defect leading to Lissencephaly-8, further analyses with the Drosophila models targeting Tmtc3 will be useful to gain more insight into this disorder." (PMID 32899411, 2020).
pancreatic cancers (1 paper, 2021). "According to the most recent update of the Network of Cancer Genes database, TMTC3 is considered as a candidate cancer gene significantly mutated in pancreatic cancers with both point mutations and CNVs that have been detected." (PMID 33503040, 2021).
squamous cell carcinoma (1 paper, 2022). A carcinoma arising from squamous epithelial cells. "TMTC3 was abnormally highly expressed in squamous cell carcinomas (SCCs), and regulated by TP63, an SCCs-specific transcription factor." (PMID 35982901, 2022).
tumor (5 papers, 2022 to 2025). "Collectively, our study clarified the molecular mechanism of TMTC3 in regulating tumor angiogenesis and highlighted the potential therapeutic combination of TMTC3 inhibitor and cisplatin, which proposed a promising strategy for the treatment of ESCC." (PMID 37752569, 2023). "The molecular mechanisms suggested that TMTC3 facilitated tumor angiogenesis by regulating Rho GTPase/STAT3/VEGFA pathway mediated by interacting with IMPDH2 Bateman domain." (PMID 37752569, 2023). "To systematically evaluate the mRNA level of TMTC3 in various cancers, we performed an in silico analysis using the Tumor IMmune Estimation Resource (TIMER) 2.0 database to analyze the mRNA expression of TMTC3 in human normal tissues and cancerous tissues." (PMID 35982901, 2022). "In vitro and in vivo assays were used to investigate the function of TMTC3 in tumor angiogenesis." (PMID 37752569, 2023). "Moreover, TMTC3 was expressed at higher levels in the central part of the tumor compared with the leading edge of ESCC tumor tissues." (PMID 37752569, 2023). "TMTC3 contributes to the O-mannosylation of E-cadherin, and dysregulation of glycosylation is one of the important mechanisms leading to tumor heterogeneity; in addition, TMTC3 is involved in the regulation of ERS, and ERS affected the malignant growth and progression of tumors." (PMID 37069941, 2023). "Hypoxic microenvironment was a key factor for inducing ER stress in tumor, therefore we supposed aberrant expression of TMTC3 might be modulated under hypoxia." (PMID 37752569, 2023). "Knockdown of TMTC3 inhibited the capability of tumor angiogenesis and ROS production in ESCC." (PMID 37752569, 2023). "Furthermore, TMTC3 was ectopically expressed in SCCs tissue arrays and enhanced the malignant phenotype in vitro and tumor growth and metastasis in vivo." (PMID 35982901, 2022). "TMTC3 acts as a binding partner for protein disulfide isomerase family A member 3 (PDIA3) and this gene’s expression plays a role in GBM-mediated pro-tumor activation of microglia." (PMID 35877430, 2022). "Furthermore, TMTC3 activates the PERK pathway, leading to the nuclear translocation of ATF4, which induces EMT and accelerates tumor cell growth and metastasis." (PMID 40302812, 2025). "In order to explore the relationship between TMTC3 and EMT, the expression of TMTC3 was analyzed in a set of 91-paired ESCC tissues with transcriptome sequencing data, and the results indicated obvious upregulation in tumor tissues compared with adjacent tumor tissues." (PMID 35982901, 2022).
cancer (4 papers, 2020 to 2023). A tumor composed of atypical neoplastic, often pleomorphic cells that invade other tissues. "TMTC3 was upregulated in various cancers, especially in ESCC, LUSC, HNSC." (PMID 35982901, 2022). "This was confirmed by our analysis since all candidate CNVs that we have identified and that were found to affect the cancer genes PMS2, APC2, POU5F1, KANSL1, DOCK8 and TMTC3 are part of this category." (PMID 33503040, 2021).
adenocarcinoma (1 paper, 2022). A common cancer characterized by the presence of malignant glandular cells. "Additionally, the expression of TMTC3 in other SCCs, including head and neck SCC (HNSC), lung SCC (LUSC), was significantly upregulated than adenocarcinoma." (PMID 35982901, 2022).
TMTC3 also shares sentences with these, for which no sentence is quoted: dystroglycanopathies (1 paper); epilepsy (1); esophageal cancer (1); Intellectual disability (1); muscular dystrophy (1); preeclampsia (1); Walker Warburg syndrome (1).